STAT3 (signal transducer and activator of transcription 3)
Diseases named in the same sentence as STAT3 in open-access papers (continued):
Sharing a sentence is not in itself a finding about the gene and the disease.
tumor (continued). "Furthermore, high NONO levels were associated with a poorer prognosis in TNBC or basal-like tumor patients who had undergone chemotherapy or radiation treatments, and both NONO and STAT3 expression was also found to contribute to drug resistance." (PMID 32724453, 2020). "Inhibition of STAT3 or STAT5 signaling or genetic deletion of fatty acid translocation enzyme CD36 inhibited activation of oxidative metabolism and induction of immunosuppressive function in tumor-invasive MDSCs, leading to CD8+ T-cell-dependent tumor growth delay." (PMID 33027968, 2020). "In GBM-derived radioresistant tumor-initiating and PROM1-positive cell populations, ARHGAP28 was upregulated upon treatment with the anticancer compound resveratrol that resulted in induction of apoptosis and elevated radiosensitivity through repression of STAT3 pathway signaling." (PMID 31083655, 2019). "Moreover, tumour-bearing DCs co-cultured with cryo-thermal eosinophils resulted in a significant down-regulation of immunosuppressive molecules, HO-1, STAT3, Foxo3, IDO2, VEGFR2 and PD-L1 as compared to tumour-bearing DCs co-cultured with tumour-bearing eosinophils." (PMID 31519961, 2019). "ATX secreted from tumor and stromal cells induces LPA, which enhances NF-κB expression via the PKC or AKT pathway, induces ATF-2 via the Rho-CDC42-p38 MAPK pathway, and activates STAT3 and STAT5, which induces the synthesis of inflammatory cytokines, chemokines, and COX-2." (PMID 31035435, 2019). "Furthermore, HO-4200 and HO-4318 significantly inhibited fatty acid synthase and pY-STAT3 and decreased the expression of STAT3 target proteins in primary platinum-resistant EOC cells, resulting in decreased expression of Ki67 and VEGF in ex-vivo human tumor specimens." (PMID 31861720, 2019). "Furthermore, we found that dynasore exerts anti-tumor effects in OS partially via inhibiting STAT3 signaling pathway but not ERK-MAPK, PI3K-Akt or SAPK/JNK pathways." (PMID 31534119, 2019). "Meanwhile, the study demonstrated that STAT3 is a direct transcriptional activator of VEGF, and inhibition of STAT3 activation by STAT3 negative mutant can significantly inhibit the VEGF expression and angiogenesis, thereby limiting the tumor growth and metastasis." (PMID 31885639, 2019). "It is tempting to speculate that a secondary effect of pharmacological STAT3 inhibition in cancer therapy may consist in a reduction of IL-15 dependent HIF-1α enrichment in NK cells, which may be expected to improve NK cell anti-tumor activity." (PMID 31681292, 2019). "In brain metastasis, the STAT3-positive reactive astrocytes not only suppressed the activation of CD8+ T cells, but also promoted the expansion of CD74+ microglial/macrophages, which produces tumor growth promoting factors, thereby benefiting metastatic tumor growth in brain." (PMID 31130637, 2019). "Unlike Stat3 that is usually oncogenic, Stat5 is a tumor inhibitor." (PMID 31614569, 2019). "Thus, therapeutic strategies preventing a precursor state transition in the CSC compartment, by inhibiting the STAT3/SLUG pathway, may lead to better tumor control and significantly prolong survival in GBM." (PMID 31652994, 2019). "Interestingly, abrogation of STAT3 signaling by knocking out the STAT3 gene did not influence the tumor formation but greatly suppressed the lung metastasis in mice." (PMID 31398937, 2019). "Considering the activation of downstream mTOR pathway, the maintenance of STAT3 phosphorylation occurred in WL group showed the leucine influence, since the group without tumour cells or bearing a tumour had constant levels of phospho-STAT3 over the three study days compared with the C group." (PMID 30975087, 2019). "Increased membrane expression of granulocyte TLR4 could impact specific signaling pathways, like NF-kappa B and STAT3, and could mediate molecular mechanisms to promote NADPH oxidase activation and, consequently, ROS production and growth suppression/decay of tumor cells." (PMID 30934946, 2019).
tumor (continued). "Instead of bulk non-CSC tumor clearance, the targeting of AKT and STAT3 is believed to be a promising anti-cancer strategy that could lead to the tumor collapse and prevention of the relapse of the disease." (PMID 31861050, 2019). "This is exampled by the induction of STAT1 and STAT3 by IFN-γ, whereby T cell differentiation is skewed toward Th1 by STAT1 and Th17 by STAT3, and that tumor cell proliferation might be restricted by STAT1 yet enhanced by STAT3—differential effects largely mediated by SOCS protein associations." (PMID 31842362, 2019). "In an adoptive transfer therapeutic strategy in mice, ablating STAT3 in CD8+ T-cells prior to transfer, allows efficient tumor infiltration and robust CD8+ T-cell proliferation, resulting in increased tumor antigen-specific T-cell activity and tumor growth inhibition." (PMID 31480382, 2019). "The obtained data proved that exosomal ZFAS1 may up-regulate STAT3 and down-regulate miR-124 to promote the proliferation, migration and invasion of ESCC cells, inhibit their apoptosis, and then lead to occurrence and development of ESCC tumor." (PMID 31775815, 2019). "It has been confirmed in mouse implanted with human HCC that inhibition of STAT3 activation by antisense oligonucleic acid not only reduces the expression of VEGF and MMP-2 but also reduces the microvascular density (MVD) of CD34 positive in tumor tissues, inhibiting tumor metastasis to the liver." (PMID 31885639, 2019). "Overexpression of STAT3 plays a key role in tumor proliferation, lots of studies indicated that inhibit the activation of STAT3 is beneficial for cancer treatment, so the expression of SOCS1, SOCS2 may inhibit tumor cell survival." (PMID 30787420, 2019). "This STAT3/STAT1 balancing would (i) reprogram mesenchymal/CSC to a non-CSC state, making them more susceptible to chemotherapy and (ii) enhance anti-tumor immunity, thereby facilitating immune cell-mediated tumor cell killing." (PMID 31684144, 2019). "Our data showed that nevirapine inhibited distant metastasis of tumor xenografts and phosphorylation of pJAK2 and pSTAT3 proteins in WRO 82‐1 cells, indicating that nevirapine exerts its anticancer effects possibly by inhibiting IL‐6/JAK2/STAT3 signaling pathway." (PMID 31631580, 2019). "Interestingly, ERK1/2 and AKT, but not STAT3 and androgen signaling, emerged as escape mechanisms leading to delayed tumor development in aged Pb-PRLΔSTAT5 mice." (PMID 31269779, 2019). "High expression of miR-454 may be one of the causes of the downregulation of VGLL4 in TNBC, and VGLL4 acts as a tumor suppressor in TNBC by interacting with STAT3 and subsequently suppresses the STAT3 signaling axis, providing potential biomarkers and therapeutic approaches for this fatal disease." (PMID 31748508, 2019). "STAT3 inhibition was further shown to induce upregulation of several intracellular signaling molecules that are involved in T-cell and monocyte activation and may be used to promote CD4 and CD8 T cell-mediated tumor elimination." (PMID 31698775, 2019). "Additionally, no significant decrease in tumor incidence or tumor grade was seen in STAT3 DN infected mice." (PMID 30833574, 2019). "Interestingly, it did also not lead to a worsening of the tumour-induced cardiac dysfunction and atrophy, a finding that was unexpected since STAT3 is an important factor for cardioprotection." (PMID 31667271, 2019). "Similarly, STAT-3 gene silencing restored DC maturation and enhanced CTL responses to tumours." (PMID 30717461, 2019). "Notably, oncogenic activation of the STAT3 pathway and overexpression of LMP1 induce the upregulation of PD-L1 in ENKTL, which may contribute to tumor escape from immune surveillance." (PMID 30935402, 2019). "Therefore, it is possible that the addition of IL-27 alongside STAT3 inhibitors may serve to further enhance their efficacy, as inhibition of STAT3 could favor STAT1-dominant signaling, promoting the anti-tumor capacity of IL-27." (PMID 31681561, 2019).
tumor (continued). "However, we observed a lack of CD45 positive cells in tumors indicating that Stat3 expression was restricted to tumor cells." (PMID 31683879, 2019). "It was speculated that the concept of non-cell-autonomous STAT3 activation of tumor cells brought about by IL-6 trans-signaling was a general phenomenon, which might also be applied to other neoplasias and cancer diseases." (PMID 31694340, 2019). "Moreover, ablation of STAT3 expression through the use of conditional knockout mice or selective STAT3 inhibitors (JSI-124) markedly reduce the expansion of MDSCs, promote accumulation of DCs and increase T-cell responses in tumor-bearing mice." (PMID 31480382, 2019). "Interestingly, in a somewhat opposing role, atypical STAT3 induction by IFN-γ during myeloid maturation by a subset of CD11b+ acute myeloid leukemia cells has been observed, which results in the upregulation of PD-L1 on tumor cells." (PMID 31842362, 2019). "Constitutive STAT3 activation in tumor-residing DCs reduces expression of MHC class II and costimulatory molecules, impairs the antigen-presenting function of DC and contributes to the expansion of tumor-infiltrating FOXP3+ T-cells and attenuates CD4+ Th cell responses." (PMID 31480382, 2019). "TGF-β also stimulates the secretion of interleukin (IL)-11 by CAFs, which then acts on colorectal cancer cells activating the gp130/STAT3 signalling pathway, which is required for tumour initiation but it is not important for the growth of tumours once established." (PMID 29701666, 2018). "Altogether, these data demonstrated the potential role of STAT3 inhibitors in cancer treatment, however these molecules cannot distinguish which activation of STAT3 could be at the origin of tumor resistance as there are no pS727 specific inhibitors." (PMID 29423098, 2018). "The expression of other STAT3-signalling cytokine, such as IL-6, could explain the absence of total tumor regression and the similar cytokine expression and immune infiltration profiles between OSM-KO mice and their WT littermates." (PMID 30559930, 2018). "Hence, we concluded a novel molecular mechanism in which ERO1α promoted the metastasis and angiogenesis of HCC through S1PR1/STAT3/VEGF-A signaling, suggesting that reagents targeting the pathway would be beneficial for inhibiting tumor metastasis and angiogenesis." (PMID 30377291, 2018). "Among well-known proteins that are overexpressed by STAT3 activation, Mcl-1, Bcl-2, Bcl-XL, and survivin are anti-apoptotic proteins that play a crucial role in cancer cell survival, cyclin D1 and c-Myc enhance proliferation, and VEGF promotes angiogenesis, which is required for tumor growth." (PMID 30109213, 2018). "Conversely, inhibition of STAT3 or STAT5 signaling or genetic deletion of the fatty acid translocase CD36 inhibits the activation of oxidative metabolism and prevents the immunosuppressive function of MDSC leading to enhanced CD8+ T cell functionality and delay in tumor growth." (PMID 30123774, 2018). "In this context, the role of STAT3 in the tumour microenvironment is critically important, and this, coupled with the fact that STAT3 is not normally activated in undifferentiated mammary epithelial cells, may go part of the way to explain this paradox." (PMID 29875329, 2018). "These authors described consistent AKT and NF-κB activation in tumor samples but not in astrocytes or oligodendrocytes of normal brain cortex and cerebellum; moreover, these authors reported a positive correlation between AKT, NF-κB activation, and tumor grade but not between them and STAT3." (PMID 30662577, 2018). "In addition, we further found that IL‐8 secreted by tumor‐driven like macrophages depended on activation of STAT3 but not NF‐κB signaling pathway." (PMID 30311406, 2018).
tumor (continued). "The results presented herein clearly showed that continual activation of STAT3 could completely reverse the inhibitory effect of SIRT2 inhibition on tumour angiogenesis, suggesting that the role of SIRT2 in tumour angiogenesis is dependent on the STAT3 signalling pathway." (PMID 30584257, 2018). "The current study demonstrated that PARK2 is a tumor suppressor gene in OS and exerts a profound anti-cancer activity in vitro and in vivo, including retarding growth, migration, invasion, metastasis, and angiogenesis by partly inhibiting the JAKT2/STAT3/VEGF pathway." (PMID 29515107, 2018). "To obtain direct evidence that Wwox inhibits STAT3 phosphorylation during tumor growth, we overexpressed either STAT3C, a constitutively active form of STAT326, or v-SRC, a protein widely shown to transform NIH3T3 cells by inducing constitutive STAT3 phosphorylation." (PMID 30154439, 2018). "Interestingly, we discovered marked sex-associated differences in lung tumor burdens due to the lack of epithelial Stat3—tumor burden was significantly reduced in female LR/Stat3Δ/Δ mice whereas tumorigenesis was markedly augmented in male counterparts." (PMID 30389925, 2018). "Similarly, bile at neutral pH seemed to contribute to deregulations of “tumour suppressor” miRNAs, such as miR‐34a and miR‐451a, but was not capable of accelerating activation of oncogenic STAT3 or other cancer‐related molecules." (PMID 29516639, 2018). "Furthermore, STAT3 acetylation but not tyrosine phosphorylation has been shown to be required to silence expression of many tumor suppressor genes such as SHP-1, CDKN2A by recruiting DNMT1 to methylate their promoter in cancer cells." (PMID 29126425, 2017). "In SCCHN, the constitutive activation of STAT3 is responsible for tumour-immune evasion, producing immunosuppressive mediators and creating an immune tolerant microenvironment, In light of this, EGFR-independent STAT3 activation could contribute to a reduced response to cetuximab." (PMID 31093349, 2017). "In addition, STAT3-blocked whole HCC cell lysates stimulated the activation of T cells and natural killer (NK) cells, and enhanced the infiltration of cytotoxic CD8+ T cells in the tumor tissues." (PMID 29115974, 2017). "In addition, the IL-6 receptor family partner gp130 levels were also not related to STAT3 activation in these tumor cell lines." (PMID 28182003, 2017). "An activated STAT3 mutant could up-regulate VEGF expression and stimulates tumor angiogenesis." (PMID 28764703, 2017). "STAT3 has been characterized as one of the major drivers of GBM, contributing to the maintenance of stemness and a mesenchymal phenotype via the IL-6/glycoprotein 130 (GP130)/STAT3 or EGF receptor (EGFR)/JAK2/STAT3 axis and leading to chemo- and radiation resistance of the tumor." (PMID 29340087, 2017). "Blockade of JAK1/STAT3 signal pathway by knocking down STAT3 significantly weakened M2 polarization of RAW264.7 macrophages induced by adenosine in coculture condition and suppressed proliferation of CT26 cells, which further confirmed the effect of TAMs on tumor growth." (PMID 29088814, 2017). "In murine xenograft tumor models injected with hepatocarcinoma, melanoma or colorectal carcinoma cells, LXA4 is able to suppress tumor growth by targeting IL-10-producing regulatory B cells (Bregs) via dephosphorylation of signal transducer and activator of transcription 3 and ERK." (PMID 28210259, 2017). "Moreover, STAT3 is a critical maintainer of cancer stem-like cells (CSC), and M2-like TAMs secret activators of STAT3 such as oncostatin M and IL10 to promote tumor cell activation and proliferation via interaction between TAMs and tumor cells." (PMID 28467800, 2017). "However, contrary to observations in other tumor cells, Stat3 and Stat5 were not involved in EPO-signaling in B16 cells." (PMID 28415825, 2017).
tumor (continued). "Importantly, this correlation between tumor STAT3 expression and response to treatment was not present in patients treated with radiotherapy alone, indicating that the observed correlation is specific for the platinum therapy." (PMID 28903353, 2017). "In addition to canonical NF-κB pathways, STAT1, STAT3, JUN, EGFR, and CEBPB were also on the top list, and these proteins may play crucial roles in tumour-induced DC signal transduction." (PMID 28350008, 2017). "In addition, tumor-infiltrating macrophages (which can constitute as much as 33% of the cell mass of a GBM) appear to have an immunosuppressive effect governed by the signal transducer and activator of transcription 3 (STAT3) pathway." (PMID 28730140, 2017). "Moreover, blocking STAT3 phosphorylation could effectively increase HLA-DR expression on CD45RA−CCR7− Treg subsets induced by TTCS, indicating that tumor-induced intracellular STAT3 phosphorylation inhibited HLA-DR expression on CD45RA−CCR7− Treg subset." (PMID 28817117, 2017). "The secretion of leptin by adipocytes activates the STAT3 signaling in CSCs and induces the expression of OCT-4 and SOX-2, in turn stimulating the expression of leptin receptor, which maintains a self-reinforcing signaling cascade to expand the CSC population and promote tumor growth." (PMID 28337221, 2017). "Essential signaling pathways involved in tumor cell proliferation and survival, such as epithelial growth factor receptor (EGFR) /Janus kinase 2 (JAK2)/ Signal transducer and activator of transcription 3 (STAT3) and mTOR pathways, have been reported to be propofol’s targets." (PMID 28962554, 2017). "Consistent with our in vitro data, we found that the level of STAT3 phosphorylation in Bazedoxifene treated tumor tissue was reduced comparing to vehicle group, supporting that Bazedoxifene suppressed tumor growth in nude mice through inhibition of IL-6/GP130/STAT3 signaling." (PMID 28672024, 2017). "However LY5 did not decrease tumor growth in xenograft mouse models and STAT3 knockdown did not induce concordant biologic effects." (PMID 28750090, 2017). "Besides negatively regulating TGF-β signaling, tumor-suppressive functions might be due to crosstalks of SMAD7 with other signaling pathways, such as JNK, NF-κB and STAT3." (PMID 28134936, 2017). "We observed that NC decreased tumor volume and weight, increased the number of TUNEL-positive cells, and showed distinctly reduced protein expression levels of phospho-STAT3 in the tumors of NC-treated mice compared to the tumors of vehicle-treated mice, consistent with our in vitro data." (PMID 29207645, 2017). "Western blot analysis of the cells extracted from the tumor tissue showed that starting from 50 mg/kg dosage it could significantly affect KIT, AKT, S6 and STAT3’s phosphorylation and the effect was more clear at 100 mg/kg dosage, which is the same with Imatinib." (PMID 29340041, 2017). "However, based on the data, we cannot conclude a STAT3-dependent expression of STAiRs in this tumor entities." (PMID 28801664, 2017). "In addition, this correlation was only present for tumor cells positive for nuclear STAT3, not for lymphocytic infiltrates (p 0.788), suggesting that the clinical effect of STAT modulation predominantly plays a role via the tumor cells themselves." (PMID 28903353, 2017). "As a redox signaling protein, Ref-1/APE1 enhances the transcriptional activity of STAT3, HIF-1α, nuclear factor kappa B, and other transcription factors to promote growth, migration, and survival in tumor cells as well as inflammation and angiogenesis in the tumor microenvironment." (PMID 28825044, 2017).